STAT3 (signal transducer and activator of transcription 3)
Diseases named in the same sentence as STAT3 in open-access papers (continued):
Sharing a sentence is not in itself a finding about the gene and the disease.
head and neck squamous cell carcinoma (165 papers, 2006 to 2026). A squamous cell carcinoma that arises from any of the following anatomic sites: lip and oral cavity, nasal cavity, paranasal sinuses, pharynx, larynx, and salivary glands. "A number of previous findings strongly suggest that the persistent activation of STAT3 in head and neck squamous cell carcinomas, accompanied by increases in STAT3 tyrosine phosphorylation, is linked to cell proliferation, differentiation, and apoptosis." (PMID 35155249, 2022). "High nuclear STAT3 expression levels are associated with favorable outcomes in head and neck squamous cell carcinomas." (PMID 34679602, 2021). "Signal transducer and activator of transcription-3 (STAT3) is an oncogenic transcription factor implicated in carcinogenesis, tumor progression, and drug resistance in head and neck squamous cell carcinoma (HNSCC)." (PMID 33206698, 2020). "A recent head and neck cancer study confirmed that mutation of PTPRT results in increased phosphor-STAT3 levels in the head and neck squamous cell carcinoma tumors." (PMID 25970784, 2015). "We recently reported the cumulative mutation profile of the PTPR gene family in cancer with a focus on PTPRT mutation leading to STAT3 activation in head and neck squamous cell carcinoma (HNSCC)." (PMID 26267899, 2015). "A recent study demonstrated that the targeted inhibition of STAT3 in tumor-associated myeloid cells increases the efficacy of radiotherapy against head and neck squamous cell carcinoma by reducing M2 macrophages and triggering T cell-mediated anti-tumor immune responses." (PMID 34638305, 2021). "Additionally, elevated STAT3 levels have been linked to poor clinical outcomes in several malignancies, including cervical cancer, esophageal squamous cell carcinoma, and squamous cell carcinoma of the head and neck (HNSCC)." (PMID 40166646, 2025). "Epigenetic silencing of SOCS3 has been shown in head and neck squamous cell carcinoma (HNSCC), which is associated with increased activation of STAT3." (PMID 23028842, 2012). "Recently, it has also been found that the exosome miR‐5100 in hypoxic head and neck squamous cell carcinoma (HNSCC) promotes CAF activation by coordinating the QKI/AKT/STAT3 axis, which further facilitates the metastasis of HNSCC." (PMID 39015555, 2024). "Phosphorylated STAT3 can directly bind to the ARG1 promoter region of myeloid-derived suppressor cells (MDSCs) in head and neck squamous cell carcinoma (HNSCC) to stimulate transcription and enhance the immunosuppressive properties of MDSCs." (PMID 39051546, 2024). "Bru-induced head and neck squamous cell carcinoma growth was similarly attributed to the disruption of the activation of STAT3 and upstream kinases such as JAK1, JAK2, and Src." (PMID 38397437, 2024). "One study suggested that lincRNA-p21 blocked the JAK2/STAT3 signaling pathway to decrease cell proliferation, thereby inhibiting the progression of head and neck squamous cell carcinoma." (PMID 37073660, 2023). "For example, phosphorylated STAT3 levels in MDSCs isolated from head and neck squamous cell carcinoma (HNSCC) patients positively correlate with ARG1 expression and suppression of autologous T cell proliferation." (PMID 36161514, 2023). "In head and neck squamous cell carcinoma, PTPRD is a known tumor suppressor and mutations lead to increased expression of signal transducer and activator of transcription 3 (STAT3)." (PMID 37731134, 2023). "STAT3 activation increases immunosuppression and found to induce immunosuppression by upregulating PD-L1 in head and neck squamous cell carcinoma." (PMID 37786649, 2023). "The STAT3/Foxp3 axis suppression in Tregs from head and neck squamous cell carcinoma contribute to Treg reprogramming and activation of antigen‐presenting cells, ultimately improved head and neck tumor growth delay." (PMID 36226375, 2023).
head and neck squamous cell carcinoma (continued). "Conversely, blocking the IL-6/JAK2/STAT3 pathway can inhibit the progression of precancerous vocal cord (oral) leukoplakia and delay the occurrence of head and neck squamous cell carcinoma (HNSCC) tumors." (PMID 37666813, 2023). "A phase 0 clinical study (NCT00696176) on STAT3 decoy oligonucleotide observed supressed level of STAT3 expression and retarded cell proliferation in head and neck squamous cell carcinomas." (PMID 37932756, 2023). "Previous studies reported that STAT3 interacted with YAP signaling in head and neck squamous cell carcinoma (HNSCC) and colorectal cancer (CRC)." (PMID 35885009, 2022). "CCR7, which binds with CCL19, stimulated the phosphorylation of Janus kinase 2 (JAK2) and signal transducer and activator of transcription 3 (STAT3) in head and neck squamous cell carcinoma cell lines (PCI-4B and PCI-37B)." (PMID 36555115, 2022). "In several HNSCC lines of human head and neck squamous cell carcinoma, it has been shown that the activation of STAT3 by phosphorylation was reversibly inhibited by GSNO, due to the S-nitrosylation of human STAT3 at the Cys259 residue." (PMID 33467703, 2021). "Nitrosylation inhibits NF-kB DNA binding in colon cancer cells and decreases STAT3 phosphorylation and activation in head and neck squamous cell carcinoma (HNSCC)." (PMID 34947954, 2021). "Radioresistant head and neck squamous cell carcinoma cells showed high expression of Snail and Twist as the activation of STAT3 levels increased." (PMID 32872659, 2020). "Importantly, studies associated with STAT3 also showed its involvement in enhancing the tumor growth and metastasis of human head and neck squamous cell carcinoma (HNSCC)." (PMID 31878245, 2019). "A close expression among molecules associated with angiogenesis: p-STAT3, VEGFA, CK2, and the MDSCs marker CD11b was found in head and neck squamous cell carcinoma (HNSCC) patients." (PMID 31057536, 2019). "As such, STAT3 has become an attractive therapeutic target in a diverse range of cancers, including bladder, ovarian and head and neck squamous cell carcinoma (HNSCC)." (PMID 31226168, 2019). "It is reported that GSNO inhibits STAT3 phosphorylation through S-nitrosylation of STAT3, to increase apoptosis of head and neck squamous cell carcinoma cells." (PMID 30988280, 2019). "Yadav et al46 found that myoferlin is bound to EHD2 protein and modulates the IL‐6/STAT3 signalling pathway, which regulates the expression of IL‐6/STAT3 downstream genes, including snail and nanog, in head and neck squamous cell carcinoma (HNSCC) cell lines." (PMID 31475450, 2019). "Coincidentally, Wang’s recent study demonstrated that STAT3 activated the MALAT1 transcriptionally activation by binding to the MALAT1 promoter region in human head and neck squamous cell carcinoma." (PMID 30591689, 2018). "Consistently, STAT3 siRNA was also demonstrated to enhance anti-tumor immunity by abrogating MDSCs' suppressive function in head and neck squamous cell carcinoma (HNSCC) in another study." (PMID 27458169, 2016). "In the present study, we investigated the potential of dihydroartemisinin (DHA) as a putative STAT3 inhibitor and its antitumor activities in head and neck squamous cell carcinoma (HNSCC)." (PMID 26784960, 2016). "Overall, the following critical issues were observed: first, DHM increased the p-STAT3-dependent autophagy by generating ROS-signaling pathways in head and neck squamous cell carcinoma." (PMID 27474168, 2016). "While STAT3 has been validated as a target for treatment of many cancers, including head and neck squamous cell carcinoma (HNSCC), a STAT3 inhibitor is yet to enter the clinic." (PMID 27027445, 2016). "We also propose a novel mechanism in which DHM increased the p-STAT3-dependent autophagy by generating ROS-signaling pathways in head and neck squamous cell carcinoma." (PMID 27474168, 2016).
head and neck squamous cell carcinoma (continued). "Here, we investigated the high phosphorylation status of STAT3 (p-STAT3) and its correlation with self-renewal markers in head neck squamous cell carcinoma (HNSCC)." (PMID 26556875, 2015). "STAT3 is activated in many cancers, including head and neck squamous cell carcinoma (HNSCC) in people." (PMID 26272737, 2015). "A specific example is the observation that enforced expression of the STAT3-DN construct suppressed the proliferation of head and neck squamous cell carcinoma cells by lowering the expression of Cyclin D1." (PMID 24995504, 2014). "An extensive body of evidence highlighting the role of STAT3 in mediating resistance to (chemo-) radiotherapy first originated from analyses of head and neck squamous cell carcinomas (HNSCC)." (PMID 25268165, 2014). "Constitutively tyrosine-phosphorylated (p) Stat3 has been found and implicated in the initiation and progression of many cancers, including breast, pancreas, head and neck squamous cell carcinoma (HNSCC), leukemias, and lymphomas." (PMID 25268166, 2014). "Interactions between NFκB and phosphorylated STAT3 also contribute to cell survival in B cell lymphomas and head and neck squamous cell carcinomas." (PMID 24170218, 2013). "In cancers of epithelial origin, Stat3 is constitutively activated in head and neck squamous cell carcinoma (HNSCC), breast cancer cell lines, ovarian cancer cell lines, and lung cancer cell lines." (PMID 16603078, 2006). "Like in head and neck squamous cell carcinoma, Interleukin-6, a representative inflammatory cytokine, could induce ferroptosis resistance by IL-6/STAT3/xCT axis." (PMID 39483473, 2024). "Moreover, GRIM-19 inhibits the aerobic glycolysis, cell proliferation, and tumorigenesis of head and neck squamous cell carcinoma by inhibiting HIF-1α/STAT3." (PMID 37118800, 2023). "For example; in esophageal squamous cell carcinoma abrogation of JAK-STAT3 signaling downregulates NF-κB signaling, in head and neck squamous cell carcinoma interfering with NF-κB reduced STAT3 signaling and in brain pericytes STAT3 cooperates with NF-κB to induce IL-6 production." (PMID 35769477, 2022). "Similarly, the reduction of STAT3 was accompanied with decreased level of aerobic glycolysis in head and neck squamous cell carcinoma." (PMID 34195079, 2021). "Furthermore, in head and neck squamous cell carcinoma, with inhibition of STAT3 activation, HIF-1α expression is repressed." (PMID 33681184, 2020). "In addition, STAT3 has been shown to be constitutively activated or over expressed in head and neck squamous cell carcinoma and lung cancers." (PMID 28878571, 2017). "Inhibition of STAT3 signaling by STAT3-targeted siRNA or treatment with Stattic, a STAT3-specific inhibitor, abrogated the arginase dependent suppressive function of M-MDSCs in head and neck squamous cell carcinoma patients." (PMID 27827921, 2016). "Long intergenic non-coding RNA p21 functions as a tumor suppressor factor through directly blocking STAT3 activity and thus inhibits G1/S transition and induces apoptosis in head and neck squamous cell carcinoma (HNSCC) cells." (PMID 38245798, 2024). "In head and neck squamous cell carcinoma (HNSCC), STAT3 promotes the transcription of lncRNA HOTAIR and its interaction with pEZH2-S21, which contributes to resistance against both CDDP and cetuximab." (PMID 39403599, 2024). "Early studies of STAT3 decoy oligonucleotides were conducted in head and neck squamous cell carcinoma (HNSCC)." (PMID 37173951, 2023). "And STAT3 expression is 10.6‐fold higher in head and neck squamous cell carcinoma (HNSCC) tissues, compared to normal mucosa tissues derived from non‐HNSCC patients, leading to that activated STAT3 is regarded as an oncogene." (PMID 35356799, 2022).
head and neck squamous cell carcinoma (continued). "Besides, CircRNA_ACAP2 could suppress EMT in head and neck squamous cell carcinoma by targeting the miR-21-5p/STAT3 signalling axis." (PMID 33981611, 2021). "For example, in head and neck squamous cell carcinoma (HNSCC), inhibiting STAT3 was shown to decrease the production of VEGF by MDSCs, although the study did not delineate between monocytic and PMN subsets." (PMID 32983128, 2020). "Persistent activation of STAT3 and deregulation of its signaling has been observed in various human cancers including head and neck squamous cell carcinoma (HNSCC)." (PMID 31575007, 2019). "PTPRT with a mutation (A1022E) in the catalytic domain resulted in increased phosphorylation of STAT3 in head and neck squamous cell carcinoma (HNSCC) cells." (PMID 29558404, 2018). "In head and neck squamous cell carcinoma (HNSCC), dihydromyricetin promotes the phosphorylation and activation of STAT3 and subsequent induction of autophagy through producing ROS." (PMID 28947908, 2017). "RhoC knockdown in HNSCC (Head and Neck Squamous Cell Carcinoma) showed a defect in activation of STAT3 in the cells and therefore a reduction in the expression of core stem cell markers like Oct3/4, Sox2, and Nanog." (PMID 27597870, 2016). "Recently, the role of STAT3 in human head and neck squamous cell carcinoma (HNSCC) has received significant attention as constitutive activation has been demonstrated in several HNSCC cell lines." (PMID 26272737, 2015). "Constitutively active STAT3 is detected in numerous malignancies, including breast, melanoma, prostate, head and neck squamous cell carcinoma (HNSCC), multiple myeloma, pancreatic, ovarian, and brain tumours." (PMID 25710482, 2015). "Inhibitors of oncogene signaling pathways such as STAT3 involved in development and progression of head and neck squamous cell carcinomas (HNSCC) have been screened by measuring nuclear morphology and anti-pSTAT3-Y705 antibody staining." (PMID 26694477, 2015). "Sen and coworkers conducted first phase 0 clinical trial using STAT3 decoy in head and neck cancer and reported that intratumoral administration of STAT3 decoy oligonucleotide abrogates target gene expression in patients with head and neck squamous cell carcinoma." (PMID 24199193, 2013). "In head and neck squamous cell carcinoma (HNSCC), tumor cells secrete MIF to activate the JAK/STAT3 pathway in myeloid cells, which in turn induces the formation of apCAFs." (PMID 41164803, 2025). "In head and neck squamous cell carcinoma, PD-L1 binds to ILF3 and IL2 to activate STAT3 for PD-L1 signaling to promote tumor progression." (PMID 40140647, 2025). "In head and neck squamous cell carcinoma, over half of the patients overexpress HGF which stimulates MET to induce the proliferation of cell cycle genes by activating STAT3 in the TME." (PMID 37727377, 2023). "Ephrin type B receptor 2 (EPHB2) in small EVs derived from head and neck squamous cell carcinoma (HNSCC) activated ephrin-B reverse signaling and induced STAT3 phosphorylation in ECs, which promoted angiogenesis both in vitro and in vivo." (PMID 34966744, 2021). "The AuNP-NUAP-STAT3d aptamer was described to potently radiosensitize head and neck squamous cell carcinoma (HNSCC) cells by combining tumor-specific radical-amplifying gold nanoclusters and tumor-specific inhibition of STAT3 signaling." (PMID 32758252, 2020). "For example, upregulation of miR-21 has been reported to be correlated with lymph node metastasis in head and neck squamous cell carcinoma (HNSCC) and actives the expression of cyclin-dependent kinase 5 through the STAT3/miRNA-21 pathway, which has also been shown to promote EMT." (PMID 33680908, 2020). "Upregulated TGF-β in head and neck squamous cell carcinoma (HNSCC) may promote STAT3 activation, which binds to the MALAT1 promoter and activates its expression, thereby inducing EMT and accelerating HNSCC metastasis." (PMID 35006436, 2020).
head and neck squamous cell carcinoma (continued). "Activation of the JAK/STAT3 pathway is correlated with upregulation of PD-L1 expression in diverse cancer types including lymphoma and head and neck squamous cell carcinoma (HNSCC)." (PMID 31511071, 2019). "This putative STAT3 inhibitor may be a new and effective drug for cancer treatment and a therapeutic approach in head and neck squamous cell carcinoma (HNSCC)." (PMID 28637459, 2017). "Thus, STAT3 is an attractive target for drug development to treat many types of cancer including head and neck squamous cell carcinoma (HNSCC)." (PMID 27027445, 2016). "It has been shown that conditioned medium collected from endothelial cells stimulate phosphorylation of STAT3, Akt, and ERK in head and neck squamous cell carcinomas." (PMID 24533454, 2014). "A network involving co-activation of NFκB and STAT3, their compensation for each other, influence on BAX/BCL-XL expression and cell survival has been described in head and neck squamous cell carcinomas." (PMID 24170218, 2013). "Leeman-Neill and colleagues also reported that Guggulsterone inhibited STAT3 and HIF-1α and suggested a biologic rationale for further clinical investigation BA for human head and neck squamous cell carcinoma (HNSCC) therapy." (PMID 21731766, 2011). "Subsequently, the HNC018 has demonstrated its anti-proliferative and anticancer activities towards the head and neck squamous cell carcinoma cell lines, along with displaying the stronger binding affinities towards the MET, STAT3, and AKT than the standard drug cisplatin." (PMID 37373393, 2023). "Conversely, STAT3 expression and nuclear localisation is higher in HPV- head and neck squamous cell carcinoma (HNSCC), suggesting that HPV may have differential effects on STAT3 activity depending on the tissue type." (PMID 32899142, 2020). "When radiotherapy and chemotherapy were combined in patients with stage III–stage IV head and neck squamous cell carcinoma (HNSCC), there was a significant increase in polymorphonuclear MDSC population from PBMC at weeks 2 and 7 of treatment, with detectable STAT‐3 and PD‐L1 expression." (PMID 32994997, 2020). "Nuclear STAT3 expression was determined by immunohistochemistry and correlated with disease-free survival in retrospective cohorts of head and neck squamous cell carcinoma (HNSCC) patients treated with cisplatin-based chemoradiotherapy (n= 65) or with radiotherapy alone (n = 32)." (PMID 28903353, 2017). "Moreover, EGCG has been proved to have inhibitory properties on cell proliferation of breast and head and neck squamous cell carcinomas (HNSCC) by suppressing the activity of EGFR, signal transducer and activator of transcription 3 (STAT3), Akt and c-fos." (PMID 25918934, 2015). "Two additional critical signaling pathways, the phosphorylation of the signal transducer and activator of transcription 3 (Stat3) pathway and the phosphatidylinositol-3-kinase (PI3K)/Akt pathway, have also been identified in head and neck squamous cell carcinoma (HNSCC) and NPC." (PMID 25607111, 2015). "Signal transducer and activator of transcription 3 (STAT3) has shown to play a critical role in head and neck squamous cell carcinoma (HNSCC) and we have recently completed clinical trials of STAT3 decoy oligonucleotide in patients with recurrent or metastatic HNSCC." (PMID 24404126, 2014). "Honokiol, isolated from the bark, seed cones and leaves of the trees of the genus Magnolia, could inhibit EGFR in head and neck squamous cell carcinoma (HNSCC) cells, resulting in reduced activities of its downstream proliferative and survival targets, such as AKT, STAT3, BCL-XL and cyclin D1." (PMID 35269825, 2022). "Besides, in head and neck squamous cell carcinoma (HNSCC) cells, IL-6 has been shown to activate the Akt, Erk1/2 and STAT3 pathways, but EMP promotion was demonstrated to be mediated specifically by the JAK/STAT3 pathway." (PMID 34361105, 2021).